SLC16A1 (solute carrier family 16 member 1)
Diseases named in the same sentence as SLC16A1 in open-access papers (continued):
Sharing a sentence is not in itself a finding about the gene and the disease.
colon carcinoma (7 papers, 2016 to 2025). "SLC16A1, a direct Wnt target gene, is coordinately regulated with other genes that promote glycolysis in colon cancer cells and it is downregulated in Frzb−/− mouse model." (PMID 37817200, 2023). "Here, we investigate this possibility and show that MCT-1/SLC16A1 is a direct target gene of β-catenin-LEF/TCF complexes in colon cancer cells." (PMID 27729975, 2016). "Previous research has demonstrated that SLC16A1 is a direct Wnt target and determines tumor sensitivity to anticancer drugs in colon cancer and could also be used as a prognostic marker for NSCLC independently." (PMID 32355273, 2020). "Here, we report that SLC16A1/MCT-1 is a direct Wnt target gene within a program of glycolysis and angiogenesis that we have defined for colon cancer." (PMID 27729975, 2016). "Since c-Myc is itself a Wnt target gene, SLC16A1 transcription is targeted both indirectly (c-Myc) and directly (LEF/TCF-β-catenin complexes) by the oncogenic Wnt pathway, perhaps underscoring the importance of MCT-1 function in colon tumors." (PMID 27729975, 2016).
medulloblastoma (6 papers, 2013 to 2022). A malignant, invasive embryonal neoplasm arising from the cerebellum. "In medulloblastomas, miR-124 was found to directly regulate SLC16A1, but miR-124 was downregulated in most tumors, which lead to an increase in SLC16A1." (PMID 35755805, 2022). "Cyclin dependent kinase 6 (CDK6) and Solute Carrier Family 16 (SLC16A1) are two identified key targets of miRNA-124 in Medulloblastoma, suggesting a role for this miRNA in cell proliferation and cell cycle." (PMID 29073265, 2017). "The authors suggest that inhibition of SLC16A1 by miR-124 decreases intracellular pH to a lethal level, leading to the observed growth inhibition in medulloblastoma cell lines upon overexpression of miR-124." (PMID 26840408, 2016). "Targets of miR-124 in medulloblastoma include SLC16A1, which regulates lactic acid export during aerobic glycolysis." (PMID 23940556, 2013). "SLC16A1 represents one of the non-neuronal targets regulated by miR-124, and its enhanced expression in medulloblastoma may confer growth advantage to tumor cells." (PMID 26041995, 2015).
liver cancer (5 papers, 2021 to 2024). An epithelial or non-epithelial malignant neoplasm that arises from the liver. "Then, we analyzed the expression of SLC16A1-14 in pan-cancer and found that they were differentially expressed in a variety of cancers, such as liver cancer and cholangiocarcinoma." (PMID 34424811, 2021). "Among these genes, SLC16A1 plays a tumor suppressor role in NSCLC, liver cancer, and oral squamous cell carcinoma." (PMID 34522968, 2021). "Alternatively, this could also be due to a PXR-mediated negative feedback loop attenuating the expression of SLC16A1, as it was demonstrated for the CYP3A4 target gene in HuH7 liver cancer cells overexpressing PXR." (PMID 34298852, 2021).
ovarian carcinoma (5 papers, 2020 to 2025). A malignant neoplasm originating from the surface ovarian epithelium. "Our study reveals that MCT4 encoded by the SLC16A3 gene shows a high level of genomic alterations in ovarian cancer patients followed by MCT1 encoded by the SLC16A1 gene." (PMID 37934721, 2023). "Compared to normal tissues, ovarian cancer tissues showed higher mRNA levels for SLC16A1 and SLC16A3, the two most important lactate transporters." (PMID 37934721, 2023). "SLC16A3, more than SLC16A1, shows a significant increase in female reproductive cancer (breast 21:0, cervical 4:1 and ovarian cancer 7:0)." (PMID 32355273, 2020). "Interestingly, in our study, we observed divergent results in the protein expression levels of SLC16A1 across different ovarian cancer cohorts." (PMID 38911368, 2024). "Notably, the solute carrier family 16 member 1 (SLC16A1) expression level in ovarian cancer was lower than in normal ovarian tissue in the Oncomine database." (PMID 34277429, 2021). "Opposed to that, increased SLC16A1 does not act as a poor prognostic marker for Ovarian cancer." (PMID 37934721, 2023).
cholangiocarcinoma (4 papers, 2021 to 2025). A carcinoma that arises from the intrahepatic biliary tree (intrahepatic cholangiocarcinoma) or from the junction, or adjacent to the junction, of the right and left hepatic ducts (hilar cholangiocarcinoma). "Furthermore, there is a significant increase in the expression of SLC16A1 in both the peritumoral tissues and the tumor tissues of cholangiocarcinoma, with expression observed in both the cytoplasm and cell membranes." (PMID 38911368, 2024).
ketoacidosis (4 papers, 2008 to 2024). "We selected 14 disallowed genes for analysis based on their identification in 2 independent studies (C1qbp, Cd302, Cxcl12, Igfbp4, Ldha, Lmo4, Maf, Oat, Pdgfra, Slc16a1, and Smad3) and/or other criteria including up-regulation in type 2 diabetes (Acot7, Ldha, and Pdgfra)." (PMID 26038943, 2015).
lung adenocarcinoma (4 papers, 2021 to 2025). A carcinoma that arises from the lung and is characterized by the presence of malignant glandular epithelial cells. "The protein expression of SLC3A2, SLC11A2, SLC1A5, SLC16A1, SLC39A7, SLC39A14 in the lung adenocarcinoma cell line A-549 and H1299 is higher than that in the normal lung epithelial cell line Beas-2B." (PMID 37973895, 2023). "The gene expression of SLC3A2, SLC16A1, SLC39A14, SLC39A7, SLC1A5, and SLC11A2 in the lung adenocarcinoma cell line A-549 and H1299 is higher than that in the normal lung epithelial cell line Beas-2B." (PMID 37973895, 2023). "In addition, our analysis of TCGA data on lung adenocarcinoma revealed that elevated expression of hypoxia-inducible factor 1A (HIF1A), lactate dehydrogenase A (LDHA), lactate dehydrogenase B (LDHB) and SLC16A1 is significantly correlated with poor prognosis." (PMID 34150616, 2021).
Obesity (4 papers, 2021 to 2024). Accumulation of substantial excess body fat. "Recent studies have revealed that homozygous Slc16a1 knockout in mice led to embryonic lethality, while the haploinsufficient mice (Slc16a1+/−) showed resistance to diet-induced obesity and associated metabolic perturbations." (PMID 39871878, 2024). "Thus, the major phenotype of intestinal Slc16a1-deleted female mice was an aggravation of diet-induced obesity, associated with increases in blood cholesterol/LDL-C levels, a reduction in metabolic rate, and aggravated hepatic steatosis." (PMID 39871878, 2024). "In conclusion, these data indicated that deletion of intestinal Slc16a1 in male mice significantly improves glucose homeostasis but did not affect diet-induced obesity, metabolic rate, and most of the blood lipid parameters." (PMID 39871878, 2024). "Hepatic deletion of Slc16a1 aggravated high-fat diet (HFD)-induced obesity in female mice, but not in male mice." (PMID 39871878, 2024). "Although homozygous Slc16a1 knockout mice are not viable, heterozygous knockout mice are protected from diet-induced obesity, insulin resistance, and hepatic steatosis." (PMID 34211098, 2021). "In obese mice, the significant increase in Slc16a1 expression during fasting might reflect a compensatory upregulation in periods of low substrate supply, even though its hepatic expression is not induced by obesity per se." (PMID 34211098, 2021).
prostate carcinoma (4 papers, 2020 to 2025). A carcinoma that arises from epithelial cells of the prostate gland. "We identified for the first time a PXR-mediated role of SLC16A1 in the transport of afatinib and the sensitivity of prostate cancer cells to this ErBb family blocker." (PMID 34298852, 2021). "Taken together, these results showed for the first time the functional role of the SLC16A1 influx transporter in PXR-mediated prostate cancer cell response to afatinib." (PMID 34298852, 2021). "SLC16A1 is overexpressed and associated with poor prognosis in various types of cancers, including prostate cancer where its expression is independent of androgen stimulation." (PMID 34298852, 2021). "In Pereira’s study, to maintain a high glycolytic phenotype, prostate cancer is effectively transported to the breast via SLC16A1 and SLC16A4.The expression level of SLC16A1 in metastatic prostate cancer cells is significantly higher than that in more restricted prostate cancer cell lines." (PMID 34631536, 2021). "Silencing SLC16A1 can significantly inhibit the growth and motor characteristics of cancer cells, high expression of SLC16A1 may stimulate prostate cancer cell activation." (PMID 34631536, 2021). "The putative presence of monocarboxylate transporters SLC16A1 (MCT1) and SLC16A7 (MCT2) is only based on immunoblotting of purified rat liver peroxisomes or immunocolocalisation in prostate cancer cells." (PMID 32266253, 2020).
cervical cancer (3 papers, 2023 to 2025). A primary or metastatic malignant neoplasm involving the cervix. "SLC16A1 is highly expressed in cervical cancer and has been associated with the infiltration of neutrophils and B cells, suggesting its involvement in the progression and immune infiltration of cervical cancer." (PMID 36894874, 2023). "As a naturally occurring compound with antitumor properties, Embelin affected cervical cancer by targeting the SLC16A1/3 pathway." (PMID 40777026, 2025). "The prepared EMB-loaded NPs effectively targeted the cervical cancer marker SLC16A1/3 to modulate glycolysis and redox pathways in combination with photothermal therapy." (PMID 39229578, 2024). "Blocking the activity of SLC16A1/3 offers a novel approach to eradicate cervical cancer efficiently." (PMID 39229578, 2024). "The SLC16A1/3 gene controls the internal and external conditions, glycolysis, and redox balance in cervical cancer cells." (PMID 39229578, 2024). "These genes were uploaded to the GEPIA database, which showed that in cervical cancer and paracancerous tissues, the expression levels of seven genes, CD47, FKBP4, IRF-1, LDHA, PDIA3, TFRC, and SLC16A1, were significantly higher in cancer tissues (p < 0.05) than in healthy tissues." (PMID 36894874, 2023).
diabetes (3 papers, 2023 to 2024). "qRT‐PCR analysis indicated significant upregulation of PDIA6 and SLC16A1 mRNA levels in individuals with diabetes when compared to healthy volunteers." (PMID 38742851, 2024). "To investigate the significance of PDIA6 and SLC16A1 in diabetes, we examined their expression in blood specimens obtained from 60 patients with T2DOPand 60 healthy controls." (PMID 38742851, 2024).
Hypertension (3 papers, 2023 to 2025). The presence of chronic increased pressure in the systemic arterial system. "In females, six loci (P < 5 × 10−8) were shared between testosterone and high blood pressure, and 3 (CYP11B1, SLC16A1, SLC22A7) of them were in DMET gene regions." (PMID 36635277, 2023).
alcoholic liver diseases (2 papers, 2020 to 2025). A disorder caused by damage to the liver parenchyma due to alcohol consumption. "Interestingly, downregulation of hepatic SLC16A1/MCT1 levels, the assumed substrate transporter for SCFAs, was observed in different liver pathology states, including alcoholic liver disease." (PMID 40100312, 2025).
Insulin resistance (2 papers, 2020 to 2021). Increased resistance towards insulin, that is, diminished effectiveness of insulin in reducing blood glucose levels. "Based on the existing literatures and our results, we speculated that our identified mutations on SLC16A1 can potentially affect its phosphorylation state, and may further lead to abnormal glucose sensing and even insulin resistance in T2D by changing the expression level of MCT1." (PMID 33240890, 2020).
lymphoma (2 papers, 2022 to 2025). A malignant (clonal) proliferation of B- lymphocytes or T- lymphocytes which involves the lymph nodes, bone marrow and/or extranodal sites. "Cancer drugs targeting SLC16A1–3 have been developed; for example, the SLC16A1 (MCT1) inhibitor AZD3965 was in a phase I clinical trial in patients with advanced solid tumors or lymphomas." (PMID 40362545, 2025).
multiple myeloma (2 papers, 2018 to 2025). "In conclusion, our study shows that selected BSG and SLC16A1 genetic variants may affect progression-free and overall survival in multiple myeloma, and correlate with various clinical parameters of MM, such as ISS stage, β-2-microglobulin and creatinine levels." (PMID 29695106, 2018). "Our present study aimed at elucidating the role played by genetic variability in BSG and SLC16A1 (MCT1) in myeloma cells." (PMID 29695106, 2018).
osteosarcoma (2 papers, 2024 to 2025). A usually aggressive malignant bone-forming mesenchymal neoplasm, predominantly affecting adolescents and young adults. "In osteosarcoma, SLC16A1 suppression has been linked to anti-tumor potential related to the NF-κB pathway 9, with high SLC16A1 expression indicating a poor overall survival rate in patients." (PMID 38911368, 2024).
renal carcinoma (2 papers, 2019 to 2021). A carcinoma arising from the epithelium of the renal parenchyma or the renal pelvis. "HPA for immunohistochemical staining on SLC16A1 protein in testicular cancer, and prostate were found to have a high signal intensity, and this was also the same in Renal cancer, uroepithelial cancer." (PMID 34631536, 2021). "SLC16A1 expression was significantly associated with ACC and PFS in the three renal cancers." (PMID 34631536, 2021).
thyroid cancer (2 papers, 2020 to 2025). "According to specific research, lower MCT1 expression in thyroid cancer is linked to elevated methylation of SLC16A1 gene promoters." (PMID 40917751, 2025).
atopic dermatitis (1 paper, 2023). "Interestingly, SLC16A1 expression is also upregulated in lesional skin of atopic dermatitis and forms part of a dynamic immune signature that reflects progressive immune activation dominated by TH2 cells." (PMID 37120582, 2023).
bladder cancer (1 paper, 2021). "Inhibiting SLC16A1 can significantly suppress the proliferation, migration and invasion of bladder cancer cells, and SLC16A1 promotes the progression of bladder cancer by affecting epithelial mesenchymal transformation and glycolysis." (PMID 34631536, 2021). "High-expressed SLC16A1 has also been found to be associated with lymph node metastasis and distant metastasis of bladder cancer, thereby showing a negative impact on the overall survival of patients." (PMID 34631536, 2021). "It has been found that SLC16A1 and SLC16A1-AS1 may together form a “head-to-head” complex unit with E2F1 promoter in muscle-infiltrating bladder cancer cells." (PMID 34631536, 2021).
Cachexia (1 paper, 2022). Severe weight loss, wasting of muscle, loss of appetite, and general debility related to a chronic disease. "Furthermore, we detected the mRNA expression of lactate transporters Slc16a1 (in muscle), Slc16a5, and Slc16a7 (in liver) and found that the levels of all three lactate transporters were upregulated in the cachexia group compared with the NC group, and the 2-DG treatment reversed this change." (PMID 36230949, 2022).
carcinoma in situ (1 paper, 2021). "SLC16A1 expression was upregulated in metastatic SKCM when compared with carcinoma in situ (P<0.01)." (PMID 34631536, 2021).
cholangitis (1 paper, 2024). An acute or chronic inflammatory process affecting the biliary tract. "Additionally, the results of IHC revealed that SLC16A1 is also expressed at higher levels in an inflammatory background (cholangitis) compared to normal tissue." (PMID 38911368, 2024).
diffuse astrocytoma (1 paper, 2021). A low-grade (WHO grade II) astrocytic neoplasm. "MCT1 (SLC16A1) and MCT4 (SLC16A3) are overexpressed in patients with GBM compared to non-neoplastic control tissue and WHO grade 3 anaplastic and WHO grade 2 diffuse astrocytoma." (PMID 34073734, 2021).
dilated cardiomyopathy (1 paper, 2024). Cardiomyopathy which is characterized by dilation and contractile dysfunction of the left and right ventricles. "These proteins are closely related to dilated cardiomyopathy (LMNA and MYH9), fibrosis (Vim), monocarboxylate transport (Slc16a1), vascular function (Cbx3 and Hnrnpn1), and endocytic trafficking (Snx5)." (PMID 39502510, 2024).
gastric cancer (1 paper, 2009). A primary or metastatic malignant neoplasm involving the stomach. "SLC5A8 and SLC16A1 have been purported to provide a mechanism for the suppression of tumour growth in colorectal and gastric cancers and are down-regulated with tumour progression." (PMID 19689820, 2009).
glaucoma (1 paper, 2025). Increased pressure in the eyeball due to obstruction of the outflow of aqueous humor. "Similarly, RNA sequencing of microglia in glaucoma animal models reveals increased expression of Slc16a1, a bidirectional transporter of lactate, pyruvate, and ketone bodies, suggesting heightened metabolic demands and functional plasticity of microglia in early stage of glaucoma." (PMID 41306973, 2025).
liver dysfunction (1 paper, 2020). "Moreover, progression of liver dysfunction, from Child–Pugh class A to C, was associated with a gradual decline in SLC16A1 expression, reaching a significant decrease in the class C livers." (PMID 32111097, 2020).
low grade glioma (1 paper, 2025). A grade I or grade II glioma arising from the central nervous system. "This study aimed to analyze the prognostic and diagnostic value of Lactate dehydrogenase A (LDHA) and solute carrier family 16 member 1 (SLC16A1) in low-grade gliomas (LGG)." (PMID 40782248, 2025).
meningioma (1 paper, 2021). A generally slow growing tumor attached to the dura mater. "Although RF predicts TIMP3, INMT and SLC16A1 followed by ALPL as the important feature genes in subtype 3, the expressions of these three genes are not consistently lower or higher than all other subtypes of meningioma, which restricts their potent of being biomarkers for meningioma." (PMID 33807688, 2021).
metabolic acidosis (1 paper, 2022). "The present work reports a patient suffering from severe, recurrent episodes of metabolic acidosis and psychomotor delay, showing a pathogenic loss-of-function variation c.747_750del in homozygosity in SLC16A1 (which codes for MCT1)." (PMID 35729663, 2022).
myeloid malignancies (1 paper, 2021). "Our study illustrates that a relatively small percentage of myeloid malignancies (10–13%) would be susceptible to SLC16A1 inhibition, but highlights phenotypic drug screening as attractive means of identifying responding cells/patients harboring metabolic dependencies." (PMID 34907165, 2021).
nephrotic syndrome, type 2 (1 paper, 2019). Any nephrotic syndrome in which the cause of the disease is a mutation in the NPHS2 gene. "The remaining two were in the non-CLA-related genes NPHS2, responsible for nephrotic syndrome type 2 and SLC16A1, which encodes a monocarboxylate transporter (MCT1), that mediates the movement of lactate and pyruvate across cell membranes." (PMID 31683770, 2019).
Parkinson disease (1 paper, 2025). A progressive degenerative disorder of the central nervous system characterized by loss of dopamine producing neurons in the substantia nigra and the presence of Lewy bodies in the substantia nigra and locus coeruleus. "For example, in Parkinson’s disease (PD), DTU analysis has revealed 23 splicing events across 19 genes, including THEM5, SLC16A1 and BCHE, in the prefrontal cortex, suggesting functional consequences for altered isoform expression." (PMID 40735840, 2025).
periapical granuloma (1 paper, 2021). Chronic nonsuppurative inflammation of periapical tissue resulting from irritation following pulp disease or endodontic treatment. "In our study, datasets of the identified active genes revealed that periapical granulomas have the highest correlation with SNPs for PPARD, TSHR, and SLC16A1 in the African population." (PMID 34539639, 2021).